CXCR4 (C-X-C motif chemokine receptor 4)
Diseases named in the same sentence as CXCR4 in open-access papers (continued):
Sharing a sentence is not in itself a finding about the gene and the disease.
tumor (continued). "The observed reduction in CXCR4+/CD105+ vessels following CXCR4 inhibition in the MOC2 model supports the therapeutic potential of targeting CXCR4 to disrupt tumor vasculature and limit tumor viability." (PMID 41210695, 2025). "Of particular interest are PLGA NPs equipped with ligands like EpCAM, CD44, and CXCR4—that guide therapies directly to tumor sites, improving both selectivity and uptake by cancer cells." (PMID 41233827, 2025). "MSC-Exo-secreted CXCR4 and cell interactions in the tumor microenvironment promote resistance to tumor cells and prevent apoptosis." (PMID 40075675, 2025). "We observed diminished tumor growth in xenografts derived from co-cultured CXCR4-knockdown GBM cells." (PMID 41041071, 2025). "Specifically, S-nitrosylation appears to modulate CD47 internalization via its interaction with CXCR4, suggesting that nitric oxide-dependent post-translational modifications influence the balance between tumor cell survival and immune clearance." (PMID 40563669, 2025). "Compared to the oe‐NC+M2pep‐Cs NPs/Plerixafor group, CXCR4 mRNA expression in the tumor tissues of the oe‐CXCR4+M2pep‐Cs NPs/Plerixafor group was significantly upregulated; while, CXCL12 mRNA expression remained unchanged." (PMID 40536774, 2025). "Aberrant expression of CXCL12/CXCR4 has been observed in diverse tumor types, and are believed to act as a crucial chemokine-chemokine receptor in promoting tumor growth.CXCL12 and CXCR4 have direct or indirect effects on tumor development." (PMID 40166682, 2025). "In contrast, the expression of IFN‐γ, IL‐12, and IL‐6 was significantly reduced in the tumor tissues of mice in the oe‐CXCR4 group." (PMID 40536774, 2025). "Whereas CXCL12/CXCR4 signaling assists tumor cells in reaching LNs, FAK/RhoA signaling controls cell migration." (PMID 40584290, 2025). "Overexpression of the chemokine receptor CXCR4 has been found to promote tumor growth, metastasis, and invasion through a variety of mechanisms, including regulation of tumor angiogenesis, immune escape, and the CXCL12/CXCR4 signaling pathway." (PMID 41473685, 2025). "Regions of high CXCR4 signal corresponded with increased presence of tumor-reactive CD8-positive effector memory T-cells in the proximal cranial bone marrow, a population characterized by durable antitumor potential." (PMID 41019666, 2025). "The CXCL12/CXCR4 axis, crucial in cancer progression and immunosuppression, involves CXCL12 from CAFs recruiting CXCR4-expressing cells that support angiogenesis and tumor growth." (PMID 40313969, 2025). "We identified IL16 and IRF4 to be broadly downregulated in tumor-infiltrating DCs, CXCR4 to be broadly upregulated, and IL18 and IL22RA2 increases to be associated with cDC2s." (PMID 39932553, 2025). "To explore the role of CXCR4 in macrophages during tumor invasion, we used macrophage-specific Cxcr4 knockout (Csf1rCreCxcr4fl/fl) mice to generate an MC38-orthotopic CRC model." (PMID 40756343, 2025). "For example, Zhongxing Liang and Tripti Khare identified that upregulation of VEGF and CXCR4 enhances tumor angiogenesis and promotes cancer cell colonization in distant organs, including the lungs, via the CXCL12/CXCR4 axis." (PMID 40777130, 2025). "Results showed that CXCR4+CD11b+ cell transfer promoted primary tumor growth and intestinal invasion, indicating CXCR4+ monocytes promoted tumor intestinal invasion." (PMID 40756343, 2025). "We discovered that CXCR4-expressing tumor vessels are significantly correlated with the histological differentiation of human OSCC microarray." (PMID 41210695, 2025). "Among these, CXCL12/CXCR4 signaling shapes a complex immunological landscape that supports tumor immune escape and progression." (PMID 40607416, 2025). "We assessed PLK4, PHOX2B, CXCR4, and cyclin D1 expression by IHC in tumor tissues from the same patients exhibiting variable differentiation status." (PMID 40860200, 2025).
tumor (continued). "The chemokine receptors CCR6, CCR7, CXCR3, CXCR4, CXCR5, and CXCR6 have the highest expression across lymphocytes, and CCR8, a known hallmark of tumour infiltrating Treg cells, is exclusively expressed on Treg cells." (PMID 39915477, 2025). "Results indicated that combining a CXCR4 inhibitor with chemotherapy prolonged survival, with higher CXCR4 expression in circulating tumor cells predicting better treatment efficacy and longer disease-free and overall survival times." (PMID 40607416, 2025). "This pathway is critical in regulating cell growth and survival, indicating that the CXCL12/CXCR4 axis contributes to tumor aggressiveness." (PMID 40433410, 2025). "In vivo, studies demonstrated that HMGA2-mediated regulation of macrophage polarization through the CXCL12/CXCR4 axis significantly promotes tumor metastasis." (PMID 40351420, 2025). "Molecular analysis showed that 44.0% of the samples isolated from circulating tumor cells (CTCs) of 48 mPCa patients were positive for CXCR4." (PMID 41347146, 2025). "The CXCL12/CXCR4 axis is crucial for fostering an immunosuppressive microenvironment that supports tumor growth and metastasis." (PMID 41245887, 2025). "This pathway is a promising therapeutic target as studies have shown that CXCR4 antagonists can improve immune responses and slow tumor progression." (PMID 41376630, 2025). "CAR‐NK cells engineered to additionally express CXCR4 have been shown to enhance direct migration towards CXCL12 in tumour‐infiltrated bone marrow compartments in mice in a haematological setting." (PMID 40159644, 2025). "This suggests that CXCR4 is a predictive marker for tumor aggression and metastasis, perhaps being involved in progenitor cell maintenance, but not contributing to metastasis directly." (PMID 39920694, 2025). "In our study, CXCR4 was highly expressed in Epithelial Cell 1, Epithelial Cell 2, and parietal cells of the tumor group by the single-cell atlas analysis in HP-positive STAD." (PMID 39886652, 2025). "CXCL12 and CXCR4 were expressed in the tumor stroma and on T cells, respectively, in dogs with epithelial malignant tumors." (PMID 40849508, 2025). "Immunofluorescence analysis revealed higher CXCR4 expression in M2 macrophages within peritumoral tissues compared to tumor tissues." (PMID 40756343, 2025). "Activation of these signal pathways leads to the development of chemoresistance and tumour progression, thus highlighting the relevance of targeting CXCR4-mediated signalling in resistant TNBC with poor therapeutic response." (PMID 41002447, 2025). "In the context of lung cancer, the signaling pathway involving chemokines, notably CXC chemokine ligand 12 (CXCL12) and its corresponding receptor, CXC chemokine receptor 4 (CXCR4), is crucial for tumor progression." (PMID 41394878, 2025). "CAFs recruit monocytes to tumor sites by releasing SDF-1 (via the SDF-1/CXCR4 axis) and CCL2 (monocyte chemoattractant protein-1, MCP-1), inducing their differentiation into M2 macrophages that further promote tumor invasion and metastasis." (PMID 41514658, 2025). "RNA sequencing results revealed significant differences in gene expression, with key genes (upregulated CXCR4, OPCML, and S100A2, and downregulated ATP1A3, CHL1, HLA-DRA, and IL-1β) associated with tumor invasiveness." (PMID 41374320, 2025). "The CXCL12/CXCR4 interaction also promotes angiogenesis, the formation of new blood vessels, which is essential for tumor growth and providing nutrients to cancer cells." (PMID 40426863, 2025). "This review highlights chemokine-mediated mechanisms, focusing on CCR9/CCL25 and CXCL12/CXCR4 axes, which promote tumor growth, metastasis, and immune evasion via PI3K/AKT and MAPK signaling." (PMID 40607416, 2025).
tumor (continued). "One prior study reported that CXCR4 expression is observed in the stromal endothelial cells of OSCC and that CXCR4 inhibition with AMD3100 induces tumor necrosis." (PMID 41210695, 2025). "Chemotherapy-induced hypoxia leads to the up-regulation of CXCL12/CXCR4 signalling, creating a vicious cycle that supports drug resistance and tumour regrowth." (PMID 41002447, 2025). "Initially, in vivo imaging demonstrated that compared to the oe‐NC group, tumor growth in the oe‐NC+M2pep‐Cs NPs/Plerixafor group was significantly reduced; while, the oe‐CXCR4 group showed increased tumor growth rates." (PMID 40536774, 2025). "The overexpression of CXCR4 in multiple cancer types and its pivotal role in tumour progression via the CXCR4/CXC12 axis makes this chemokine receptor an attractive target for cancer diagnosis, response assessment and patient profiling." (PMID 40307933, 2025). "Our findings demonstrated that the SDF-1/CXCR4 axis promotes tumor stemness by directly acting on CXCR4, as well as by potentially enhancing PCSC stemness via downstream β-catenin signaling pathway activation." (PMID 40735647, 2025). "Inhibiting CXCR4 can reduce tumor growth and potentially restore or enhance the efficacy of immune checkpoint inhibitors." (PMID 40909292, 2025). "Flow cytometry results demonstrated that compared to the oe‐NC group, the oe‐NC+M2pep‐Cs NPs/Plerixafor group showed a significant increase in the M1 TAM marker CD80 in mouse tumor tissues, whereas the oe‐CXCR4 group showed a marked decrease." (PMID 40536774, 2025). "The single-cell atlas of HP-positive STAD revealed that CXCR4 was highly expressed in Epithelial Cell 1, Epithelial Cell 2, and parietal cells of the tumor group." (PMID 39886652, 2025). "As chemotaxis is an important biological behavior process often used by tumor cells for metastasis and invasion CXCR4, its ligand CXCL12, and atypical receptor ACKR3 are overexpressed in many human cancers." (PMID 40427609, 2025). "For example, targeting the CXCR4 receptor has been explored in other cancers, with drugs like Plerixafor (AMD3100) being used to block CXCR4, thereby mobilizing hematopoietic stem cells and potentially influencing tumor progression." (PMID 40087784, 2025). "Single-cell atlas of HP-positive STAD revealed that CXCR4 is highly expressed in Epithelial Cell 1, Epithelial Cell 2, and parietal cells of the tumor group." (PMID 39886652, 2025). "For instance, CXCL12 binding to CXCR4 promotes tumor cell proliferation while suppressing NK cell infiltration." (PMID 41445742, 2025). "A combination of anti-PD-1 and anti-CXCR4 immunotherapy modulates tumour infiltration of CD8+ T cells can hence promote an anti-tumour immune response and improve survival rates." (PMID 40852716, 2025). "Cellular interaction and immunohistochemical analysis proposed MIF‐(CD74 + CXCR4) signaling pathway as a key mechanism by which malignant cells influence immune cells within the tumor microenvironment." (PMID 40018995, 2025). "CXCR4 signalling promotes T-cell proliferation, potentially counteracting tumour-induced immunosuppression." (PMID 41243106, 2025). "IHC analysis revealed that CD74 and CXCR4 were highly expressed in the infiltrating immune cells within the tumor tissues." (PMID 40018995, 2025). "Initial Western blot results demonstrated a significant decrease in CXCR4 protein expression in the tumor tissues of mice treated with oe‐NC+M2pep‐Cs NPs/Plerixafor compared to the oe‐NC group; while, CXCL12 protein levels remained unchanged." (PMID 40536774, 2025). "Currently, the CXCL12/CXCR4 axis is thought to involve several tumor‐related signaling pathways in the HCC process, such as nuclear factor (NF)‐κ B, PI3K/protein kinase B (AKT), and c‐Jun amino‐terminal kinase (JNK)." (PMID 40145607, 2025). "To detect the co-localization of CXCR4+ vascular structures with endothelial markers, we stained tumor tissues of both MOC1 and MOC2 in serial sections with CD105, CD34, and D2-40." (PMID 41210695, 2025).
tumor (continued). "In fact, a combination of PD-1 and CXCR4 inhibition resulted in enhanced T-cell expansion and tumor cell death in pre-clinical models." (PMID 40230862, 2025). "Dual blockade strategies of immune checkpoint inhibitors and CXCR4 inhibitors will condition the tumour microenvironment, re-increase T cell infiltration, and improve therapeutic outcomes from immunotherapy." (PMID 41002447, 2025). "CXCR4, which is involved in tumour invasion, was studied for its interaction with cancer-associated fibroblasts (CAFs) within the TME." (PMID 41312167, 2025). "One of the main players in this resistance is the CXCR4/CXCL12 signalling axis that is known to play a role in promoting tumour progression, metastasis, survival and remodelling the tumour microenvironment." (PMID 41002447, 2025). "Compared with those in the Mod group, the CXCR4 protein levels in the tumor tissues of the PVT, Taxol and PVTM + Taxol groups were downregulated." (PMID 40076586, 2025). "In this research, no statistical differences in the expression levels of MIF, CD74, and CXCR4 were found between tumor and normal groups." (PMID 40066443, 2025). "Compared to the oe‐NC+M2pep‐Cs NPs/Plerixafor group, the number of T cells and B cells was significantly decreased in the tumor tissues of mice in the oe‐CXCR4+M2pep‐Cs NPs/Plerixafor group." (PMID 40536774, 2025). "This mutation was also linked to higher metastatic efficiency, as evidenced by increased tumor budding, higher CXCR4 expression, and enhanced Akt activation, which collectively contribute to increased cell survival, invasion, and intravasation." (PMID 40075837, 2025). "In the last years, the influence of the CXCR4 axis in tumor pathogenesis has become increasingly relevant." (PMID 40142155, 2025). "A previous study reported that inhibiting CXCR4 with AMD3100 induces tumor cell death and enhances the efficacy of the chemotherapeutic agent cisplatin." (PMID 41210695, 2025). "The rationale behind this approach is to first simultaneously deplete cancer-associated fibroblasts (CAFs), which are a major aspect of the tumour stroma, while inhibiting CXCR4-mediated immune suppression." (PMID 41002447, 2025). "Biologics, such as mAbs and ligand traps, selectively target the receptor (CXCR4) or ligand (CXCL12) to inhibit a signalling loop that promotes tumour survival, immune suppression, and chemoresistance." (PMID 41002447, 2025). "The dual inhibition of TGFβ and CXCR4 is a combination of the inhibition of two distinct yet interrelated pathways involved in tumor progression, metastasis, and stemness." (PMID 41348904, 2025). "CXCL12, primarily acting through its receptor CXCR4, is known to play a pivotal role in tumor growth, metastasis, and immune evasion." (PMID 40481962, 2025). "The CXCR4 overexpression participates in tumor growth, metastatic dissemination, and cancer relapse." (PMID 40066443, 2025). "In fact, pretreatment of tumor cells with TNF-α increased the expression of CXCR4 at both mRNA and protein levels." (PMID 39609700, 2024). "Certain proteins, such as HER2, kinase insert domain receptor (KDR), CD49d, C-X-C motif chemokine receptor 4 (CXCR4), and CD44, were found to be associated with tumor recurrence or distant organ metastasis." (PMID 38542535, 2024). "CXCR7, which is highly expressed in TECs, plays a key role in transendothelial migration mediated by CXCL12/CXCR4 in CXCR4 (+)CXCR7 (+) human tumor cells." (PMID 39408814, 2024). "We aimed to investigate the therapeutic potential of targeting the chemokine receptor CXCR4, which is involved in angiogenesis and tumor progression, using the CXCR4 inhibitor AMD3100, in combination with cisplatin." (PMID 39001388, 2024). "Among others, C-X-C motif chemokine receptor 4 (CXCR4) is highly expressed in patients affected with ACC and ex-vivo analyses provided evidence that the expression level on the tumor cell surface is tightly linked to the proliferation index." (PMID 38896128, 2024).
tumor (continued). "In vivo, plerixafor and tamoxifen significantly reduced tumor growth compared to tamoxifen alone, with a decrease in tumor CXCR4 expression." (PMID 38612911, 2024). "In ovarian cancer, CXCR4 and CCR9 chemokine receptors cause resistance of tumor cells to apoptosis, promote their escape from the immune system, and increase angiogenesis." (PMID 38770000, 2024). "The expression of CXCR4 and CXCR7 are the hallmark of mesenchymal GBM cells, which are typically found in the hypoxic necrotic regions of the tumor." (PMID 37692522, 2024). "CXCR4 is mainly expressed in the membrane and cytoplasm of tumor cells, and cytoplasmic coloration reflects the internalization of the receptor in response to agonist stimulation." (PMID 38524630, 2024). "As discussed, the CXCL12/CXCR4 axis is involved in tumor angiogenesis and metastasis of tumor cells to distant organs." (PMID 39070795, 2024). "CPI-203 and IQS-01.01RS (CXCR4 inhibitor) co-treatment reduced tumor burden by downregulating MYC and p-AKT as well as enhancing apoptosis in DLBCL." (PMID 39580422, 2024). "The SDF/CXCR4 axis plays a crucial role in several mechanisms that promote tumor growth and metastasis." (PMID 38390333, 2024). "The role of CXCR4 in promoting tumor cell proliferation, invasion, and metastasis underscores its significance as a potential therapeutic target in GBM." (PMID 39162901, 2024). "Tumor microenvironments in the lung favor inflammation by exploiting the SDF/CXCR4 axis, leading to angiogenesis, tumor progression, and metastasis." (PMID 38390333, 2024). "For example, the CXCR4 antagonist IS4 has been shown to reduce tumor metastasis in prostate and melanoma cell lines." (PMID 39596815, 2024). "Consistent with recent findings, most tumor-infiltrating B cells were in cluster 1, which exhibited a highly activated phenotype, expressing Cd86 and Cxcr4." (PMID 39718828, 2024). "Proangiogenic subtypes of BMDCs such as CD61+, Gr-1+CD11b+, VEGFR2+, and CXCR4+ in the circulating blood were analyzed in tumor-bearing mice using flow cytometry after CPA or 5-Fu treatment." (PMID 39119610, 2024). "MDA-MB-231 cell line was selected for evaluating the interaction of anti-CXCR4-NaGdF4 NDs with cancer cells because the human TNBC is a typical refractory tumor." (PMID 38982161, 2024). "Several studies report that inhibiting CXCR4 by its antagonist reduces tumor growth in vitro and in vivo by hindering cell proliferation, migration, and invasion." (PMID 39033780, 2024). "CXCL12 and its receptor; C-X-C motif chemokine receptor 4 (CXCR4) are involved in recruitment of tumor-promoting macrophages." (PMID 39003350, 2024). "Macrophage exclusion from the tumor by inhibition of C‐X‐C motif chemokine receptor 4 (CXCR4) was shown to reduce post‐irradiation tumor revascularization in a small phase I/II trial." (PMID 38899374, 2024). "Our data demonstrate that similar to circulating neutrophils, tumor‐infiltrating neutrophils also undergo an aging process characterized by the upregulation of CXCR4 expression." (PMID 39447112, 2024). "The SDF-1/CXCR4 axis is involved in the proliferation, angiogenesis, anti-apoptosis and metastasis of tumor cells." (PMID 38244066, 2024). "Higher infiltration of CXCR4+ neutrophils in LSCC was correlated with smoking history and advanced tumor stage and was associated with worse survival outcomes." (PMID 39447112, 2024). "CXCR4+ tip cells dispersed in the tumor core and typically co-localized with epithelial or malignant cells." (PMID 39345334, 2024). "The chemotactic migration induced by CAF-derived SDF-1 and its interaction with CXCR4 on CRC cells substantiates the operational SDF-1/CXCR4 signaling axis in promoting tumor aggressiveness." (PMID 39195225, 2024). "One hundred three of 152 (67.8%) of scans demonstrated CXCR4-positive tumor burden, which were obtained from 95 different patients." (PMID 38082196, 2024).